PALB2 (partner and localizer of BRCA2)
Diseases named in the same sentence as PALB2 in open-access papers (continued):
Sharing a sentence is not in itself a finding about the gene and the disease.
ovarian carcinoma (continued). "There is also an indication that PALB2 is haploinsufficient for tumour suppression, since almost all PALB2 truncating mutations conferring a risk for breast/ovarian cancer are monoallelic." (PMID 29387807, 2017). "Germline inactivating mutations in PALB2 are associated with an increased risk of breast and ovarian cancer." (PMID 28279176, 2017). "The rarity of mutations in PALB2 and the rarity of some of the other cancers likely to be involved (pancreatic, male breast cancer, ovarian cancer, prostate cancer) make the estimation of the risk (if any) extremely challenging." (PMID 27099641, 2016). "Two protein truncating mutations in PALB2 (c.1592delT, p.Leu531Cysfs and c.3113G > A, p.Trp1038*) were included on the iCOGS and genotyped in 16,287 ovarian cancer cases and 23,491 controls." (PMID 27099641, 2016). "We examined the entire coding sequences of the BRCA1 and BRCA2 genes and genotyped a recurrent mutation of the PALB2 gene (c.509_510delGA) in 121 women with familial and/or early-onset breast or ovarian cancer from Southern Poland." (PMID 26843898, 2016). "Beyond the high penetrance BRCA1/2 genes, mutations of several cancer susceptibility genes, including ATM, CHK2 and PALB2, have been shown to associate, with a moderate penetrance, with familial breast and/or ovarian cancers." (PMID 27599564, 2016). "Mutations in the BRCA1, BRCA2 and PALB2 genes are well-established risk factors for the development of breast and/or ovarian cancer." (PMID 26843898, 2016). "Accumulating this evidence is challenging due to the very low frequency of women with PALB2 mutations, even in affected women with a strong family history of breast and ovarian cancer." (PMID 27099641, 2016). "Inherited mutations in the BRCA2-interacting protein, PALB2, are known to be associated with increased risks of breast, pancreatic, and, likely, ovarian cancer." (PMID 26075229, 2015). "PALB2 mutations have been associated with predisposition to pancreatic and ovarian cancers, which were both observed in families identified in our study." (PMID 23448497, 2013). "It is worthwhile to mention that 18 of these 33 families (55%) had a family member with ovarian cancer, who was confirmed to carry the familial PALB2 mutation." (PMID 23586058, 2013). "Two PALB2 mutation carriers were identified in a study of 339 unrelated ovarian cancer cases of Polish descent." (PMID 23302520, 2013). "There is less evidence that PALB2 mutations predispose to ovarian cancer, although founder mutations have been identified in ovarian cancer patients from Poland and Russia." (PMID 24025454, 2013). "The role of PALB2 in ovarian cancer is uncertain, as there have been few documented ovarian carcinoma cases harboring germline mutations in this gene." (PMID 23302520, 2013). "After BRCA2/FancD1, two other genes, namely, BRIP1/FancJ and PALB2/FancN, were described as FA and breast and ovarian cancer susceptibility genes, suggesting a strong genetic connection between FA and hereditary breast and ovarian cancer." (PMID 23344037, 2013). "PALB2 sequence variants identified in 132 Spanish breast/ovarian cancer families with pancreatic cancer cases." (PMID 23935836, 2013). "Two (0.6%) PALB2 mutation carriers were reported in a study of 360 ovarian cancer cases that were also screened for BRCA1, BRCA2 and other recently described cancer susceptibility genes." (PMID 23302520, 2013). "Two other genes involved in FA and related to breast or ovarian cancer predisposition are PALB2/FANCN and RAD51C/FANCO." (PMID 22778927, 2012). "Downstream proteins such as FANCD1/BRCA2, FANCJ/BRIP1 and FANCN/PALB2 have been linked to elevated risk of breast and ovarian cancers." (PMID 20043851, 2009). "In recent years, PALB2 has emerged as one of the most important cancers predisposing genes, conferring an increased risk of breast, pancreatic, gastric and ovarian cancer." (PMID 41488399, 2026).
ovarian carcinoma (continued). "In addition, PALB2 variants were identified in one case each in Korean ovarian cancer and pancreatic cancer cohorts." (PMID 39409938, 2024). "A multigene germline mutation analysis of ovarian cancer patients at the University of Washington revealed that 18% of patients carried pathogenic mutations in susceptibility genes and that PALB2 and BARD1 were significantly associated with the occurrence of ovarian cancer." (PMID 38817903, 2024). "Our study differs from the research conducted by Manchanda et al31 on the cost-effectiveness of population-based testing for BRCA1, BRCA2, RAD51C (OMIM 602774), RAD51D (OMIM 602954), BRIP1 (OMIM 605882), and PALB2 mutations for preventing breast and ovarian cancer in the following ways." (PMID 38353949, 2024). "Extensive studies showed that the carriers of monoallelic PALB2 pathogenic variants (PVs) are predisposed to develop multiple types of cancer, including breast, pancreatic, and ovarian cancers; the carriers of biallelic PALB2 PVs can cause the subtype N of Fanconi anemia (FA-N)." (PMID 37511102, 2023). "Family history information was not available from the COG cohort and thus we could not determine if the patients who had germline variants in BRCA1, BRCA2, or PALB2 had a family history of breast or ovarian cancer." (PMID 38110397, 2023). "However, data about the prevalence of germline PALB2 variants in breast and ovarian cancers from Middle Eastern ethnicity is still scarce." (PMID 37169825, 2023). "However, the largest study to-date of patients with PALB2 mutations including more than 500 families found a relative risk of ovarian cancer of 2.91 (95% CI 1.40-6.04) compared to country-specific population incidence." (PMID 35159349, 2022). "The PALB2 mutation has rarely been found in ovarian cancer patients." (PMID 34439348, 2021). "Whether the magnitude of risk is sufficiently high to warrant the inclusion of PALB2 in cancer gene panels for ovarian cancer risk testing is unclear; much larger sample sizes will be needed to provide sufficiently precise estimates for clinical counselling." (PMID 32546565, 2021). "PALB2 PGVs and CHEK2_1100delC together account for ~2.5% of familial breast/ovarian cancer risk." (PMID 34113003, 2021). "In Poland there is little data about association of PALB2 mutations with ovarian cancer." (PMID 33670479, 2021). "PALB2 mutations predispose patients to a spectrum of cancers, including breast and ovarian cancers." (PMID 34946951, 2021). "Germline mutations in PALB2 were reported to correlate with an increased risk of ovarian cancer." (PMID 33670479, 2021). "Some studies highlight a possible association between PALB2 mutations and ovarian cancer." (PMID 32733558, 2020). "Numerous studies have demonstrated that biallelic mutations in PALB2 resulted in a subtype of Fanconi anemia (FA-N), while monoallelic PALB2 mutations predispose carriers to multiple cancers such as breast, pancreatic, and ovarian cancers." (PMID 32185139, 2020). "To date, several studies have indicated that PALB2 mutations are associated with ovarian cancer." (PMID 32185139, 2020). "Segregation analysis from large international consortia has been used to calculate ovarian cancer risks in RAD51C, RAD51D, and PALB2, and could be applied to other moderate risk ovarian cancer genes." (PMID 33086730, 2020). "Population panel testing for BRCA1/BRCA2/RAD51C/RAD51D/BRIP1/PALB2 gene mutations is the most cost-effective genetic-testing strategy in general-population women and can prevent thousands more breast and ovarian cancers than current clinical-criteria based approaches." (PMID 30400647, 2018). "Two of the nonsense mutations (p.C675X and p.E1013X) in BRCA1, 7 of the frameshift (p.N1626*11, p.N3024*16, p.Q1429*8, p.L2092*6, p.K1057*7 (x2), and p.F1546*21) in BRCA2 and a single frameshift (p.Q60*6) in PALB2 would predispose the carrier to breast/ovarian cancer." (PMID 29641532, 2018).
ovarian carcinoma (continued). "Furthermore, in breast and/or ovarian cancer patients, several single nucleotide variants (SNVs) were detected in the PALB2 coding region." (PMID 28279176, 2017). "Biallelic inactivating germline mutations in the PALB2 gene lead to Fanconi anemia (Fanconi anemia type N), whereas monoallelic mutations are associated with an increased risk of breast, pancreatic, and possibly ovarian cancer." (PMID 28279176, 2017). "To date, the spectrum of malignancies associated with PALB2 mutations remains unclear, however mutations confer increased risks for pancreatic cancer and possibly ovarian cancer." (PMID 25225577, 2014). "Hereditary ovarian cancer is probably underestimated, since recent studies highlight new susceptibility genes (RAD51C, RAD51D, PALB2) that might predispose for ovarian cancer, but their exact prevalence is still under investigation." (PMID 23536787, 2013). "The occurrence of PALB2 mutations in ovarian cancer has been less studied but is probably rare." (PMID 23587053, 2013). "Additionally, carriers of pathogenic PALB2 variants may consider risk-reducing salpingo-oophorectomy between the ages of 45 and 50 to lower the risk of ovarian cancer." (PMID 39409938, 2024). "This economic evaluation found that population-based BRCA1, BRCA2, and PALB2 testing among unselected women was cost-effective for the prevention of breast and ovarian cancer and remained cost-effective in extensive 1-way sensitivity analyses." (PMID 38353949, 2024). "A few studies reported PALB2 germline LGRs in patients with breast, pancreatic, and ovarian cancers." (PMID 39682206, 2024). "However, after intensive treatment with ChT and radiotherapy, which she received for her B-ALL and TNBC and a known pathogenic variant in the PALB2 gene, her risk for the development of new primary cancers other than breast and ovarian cancers, particularly pancreatic cancer, may be substantial." (PMID 38817905, 2024). "Increasing genetic referral and expanded testing resulted in higher estimated rates of risk-reducing surgery and lower incidence of breast and ovarian cancer in relatives of probands with a P/LP variant in BRCA1, BRCA2 or PALB2." (PMID 39766065, 2024). "We aimed to investigate the GC-5′ss of the breast/ovarian cancer susceptibility genes, ATM (exon 50), BRIP1 (exon 1), and PALB2 (exon 12), and their dysregulation induced by DNA variants." (PMID 39518003, 2024). "On the other hand, ATM and PALB2 are considered moderate penetrance genes in breast and ovarian cancer, and MSH6, PMS2, and EPCAM are considered moderate penetrance genes in LS CRC." (PMID 38201484, 2023). "RAD51C mutations have previously been reported to increase the risk for breast and ovarian cancer and to also be causative for a recessively inherited Fanconi anemia-like disorder, similar to BRCA1, BRCA2 and PALB2 mutations." (PMID 37578974, 2023). "BRIP1 is instead included on the corresponding gene panel for ovarian cancer predisposition, together with BRCA1, BRCA2, PALB2, RAD51C, RAD51D and the Lynch syndrome genes." (PMID 37563628, 2023). "Germline PVs in the HR-related genes BRIP1, PALB2, RAD51C and RAD51D have an established role in increasing a patient's risk of ovarian cancer." (PMID 36805919, 2023). "Germline PVs/LPVs in PALB2 have also been identified in ovarian cancer and pancreatic cancer patients." (PMID 37169825, 2023).
ovarian carcinoma (continued). "Through modified segregation analysis including families from this study, risk estimates for breast and ovarian cancer have been refined for PTVs in RAD51C, RAD51D, PALB2 and for the moderate penetrance missense variant BRCA1 c." (PMID 37563628, 2023). "Consensus guidelines for hereditary breast and ovarian cancer include management recommendations for pathogenic/likely pathogenic (P/LP) variants in ATM, CHEK2, PALB2, and other DNA damage repair (DDR) genes beyond BRCA1 or BRCA2." (PMID 35626031, 2022). "Genotyping of 21 mutations in BRCA1, BRCA2, RAD51C, PALB2, and CHEK2 genes was performed for 102 BOT patients, 167 cases of ovarian cancer G1, and 1743 healthy controls." (PMID 35313928, 2022). "Other genes implicated in ovarian cancer, BRIP1, RAD51D, PALB2, and RAD51C, had a yield of 1.1% (n = 12), 0.8% (n = 9), 0.3% (n = 3), and 0.09% (n = 1), respectively." (PMID 35971132, 2022). "Recently, 21 founder and recurrent mutations in BRCA1/2, PALB2, RAD51C, and CHEK2 genes have been analyzed in a large Polish case-control study including 2270 ovarian cancer patients and 1743 controls." (PMID 35313928, 2022). "Based on the studies in breast and ovarian cancer, BRCAness are present in about 20% of breast cancer and 45% of ovarian cancer, such as the mutations in RAD51C, NBS1, BRIP1, and PALB2." (PMID 36497135, 2022). "Monoallelic pathogenic variants in FANCD1/BRCA2, FANCS/BRCA1, FANCJ/BRIP1, FANCM, FANCN/PALB2, and FANCO/RAD51C have been linked to familial breast and ovarian cancer." (PMID 36428697, 2022). "Women with disease-causing gene changes (faults/mutations) in BRCA1, BRCA2, PALB2, CHEK2 and ATM are at an increased risk of developing certain types of cancer—specifically breast (all genes) and epithelial ovarian cancer (only BRCA1, BRCA2, PALB2)." (PMID 35681696, 2022). "On contrary, the low-grade ovarian cancer is associated with BRCA1 and PALB2 mutations and presents worse survival among BRCA1 carriers." (PMID 35313928, 2022). "PALB2 was initially reported to occur at similar frequency in ovarian cancer to controls in large European cohorts." (PMID 35159349, 2022). "The aim of the study was to analyze the prevalence and association of recurrent founder germline mutations in BRCA1, BRCA2, RAD51C, PALB2, and CHEK2 genes with ovarian cancer risk among unselected patients in the Polish population." (PMID 33670479, 2021). "PALB2, a partner and localizer of BRCA2, is a Fanconi anemia group protein (FANCN), which permits stable intranuclear localization and accumulation of BRCA2 and can cause pancreatic, breast, and ovarian cancer." (PMID 33413558, 2021). "We recommend that in Poland all women with ovarian cancer and first-degree female relatives should be tested for the panel of 18 founder mutations in BRCA1, BRCA2, PALB2, and RAD51C." (PMID 33670479, 2021). "The aim of the study was to analyze the frequency and magnitude of association of 21 recurrent founder germline mutations in BRCA1, BRCA2, PALB2, RAD51C, and CHEK2 genes with ovarian cancer risk among unselected patients in Poland." (PMID 33670479, 2021). "Testing of 302 cases with ovarian cancer detected two PALB2 PGVs, (c.2167_2168delAT; p.[Met723ValfsTer21] and c.3113G>A; (p.Trp1038Ter]) (OR = 3.47, 95% CI = 0.61–17.07, P = NS), and one with CHEK2_c.1100delC (OR = 1.04, 95% CI = 0.09–7.49, P = NS)." (PMID 34113003, 2021).
ovarian carcinoma (continued). "Association analysis in an additional 14 135 ovarian cancer cases and 28 655 controls genotyped through OCAC and the UK Biobank provided further support for PALB2 as a HGSOC susceptibility gene." (PMID 32546565, 2021). "Several founder mutations in the BRCA1, BRCA2, PALB2, RAD51C, and CHEK2 genes are associated with breast and ovarian cancer." (PMID 33670479, 2021). "Genotyping of 21 mutations in BRCA1, BRCA2, RAD51C, PALB2, and CHEK2 genes was performed for all 2270 ovarian cancer patients and 1743 healthy controls." (PMID 33670479, 2021). "In Poland, founder mutations in BRCA1, BRCA2, PALB2, CHEK2, and RAD51C have been associated with familial breast and ovarian cancer." (PMID 33670479, 2021). "Monoallelic mutations in five of these genes (BRCA1, BRCA2, PALB2, BRIP1 and RAD51C) increase the susceptibility to breast/ovarian cancer and are used in clinical diagnostics as bona-fide hereditary cancer genes." (PMID 32235514, 2020). "In this study, we aim to gain insight in the germline mutation spectrum of ATM, BARD1, BRIP1, ERCC4, PALB2, RAD51C and RAD51D in breast and ovarian cancer families from Spain." (PMID 32756499, 2020). "Based on the latest National Comprehensive Cancer Network Guideline, PALB2 is categorized as a gene associated with breast cancer risk, whereas BRIP1 and RAD51C are categorized as genes associated with ovarian cancer risk." (PMID 32269964, 2020). "Multiple gene panel studies have revealed that inherited breast and ovarian cancers rarely harbor germline mutations of FA genes, including BRIP1/FANCJ, PALB2/FANCN, and RAD51C/FANCO." (PMID 32269964, 2020). "Monoallelic mutations in five FA genes (BRCA1, BRCA2, PALB2, RAD51C, BRIP1) have now been confirmed to predispose to breast or ovarian cancer while biallelic mutations in these genes cause FA3." (PMID 31467304, 2019). "Other members of the FANCG complementation group include breast and ovarian cancer associated genes; FANCO (RAD51C), FANCS (BRCA1), BRCA2 (FANCD1), BRIP1 (FANCJ) and PALB2 (FANCN)." (PMID 28591191, 2017). "In this study, we have genotyped 68 MBC patients for the known breast or ovarian cancer associated mutations in the Finnish population in CHEK2, PALB2, RAD51C, RAD51D, and FANCM genes." (PMID 28874143, 2017). "An increased risk of breast or ovarian cancer is associated with monoallelic mutations in a subset of these genes (BRCA1, BRCA2, BRIP1, PALB2, RAD51C)." (PMID 28874143, 2017). "When combined with mutations in genes that cause hereditary breast and ovarian cancer such as BRCA1, BRCA2, PALB2 and RAD51C, depletion of Rad52 is shown to be synthetically lethal." (PMID 28722656, 2017). "The promoter methylation of PALB2 has been investigated in the context of breast and ovarian cancer." (PMID 27902704, 2016). "We screened 121 women with familial and/or early-onset breast or ovarian cancer for mutations in BRCA1, BRCA2 and PALB2." (PMID 26843898, 2016). "At least 5 of the 17 known FA genes, D1/BRCA2, J/BRIP1, N/PALB2, O/RAD51C and S/BRCA1, are well-established breast and/or ovarian cancer susceptibility genes." (PMID 26085575, 2015). "Several FA genes are also breast and ovarian cancer susceptibility genes (FANCD1/BRCA2, FANCJ/BRIP1, FANCN/PALB2, FANCO/RAD51C, and FANCS/BRCA1)." (PMID 26430909, 2015).